CYP2R1 (cytochrome P450 family 2 subfamily R member 1)
Diseases named in the same sentence as CYP2R1 in open-access papers (continued):
Sharing a sentence is not in itself a finding about the gene and the disease.
Allergy (3 papers, 2006 to 2025). An allergy is an immune response or reaction to substances that are usually not harmful. "In addition, the VDR and CYP2R1 genes map to chromosome 12q and 11p respectively, and both of these chromosome locations include susceptibility loci for allergic diseases according to genome-wide linkage analysis studies." (PMID 26177022, 2015). "Genotype distributions of CYP2R1, GC, and VDR polymorphisms in patients with allergy symptoms, autism spectrum disorder, and Hashimoto’s thyroiditis." (PMID 41340975, 2025). "For CYP2R1 rs1562902, genotype distributions showed moderate variation among groups: the CT heterozygous form was relatively common in both the allergy and Hashimoto’s thyroiditis groups." (PMID 41340975, 2025). "The relationship between vitamin D and allergic diseases has increasingly attracted attention in recent years, and accordingly, SNPs of VDR and CYP2R1 have also been reported to be associated with some immune disorders." (PMID 26177022, 2015). "The relationship between the SNPs of CYP2R1 and susceptibility to allergic diseases has not been fully explored." (PMID 26177022, 2015). "A similar trend was observed for CYP2R1 rs2060793; the GG genotype appeared slightly more frequently in the ASD and allergy groups, while the AG heterozygous form predominated in the Hashimoto’s thyroiditis group." (PMID 41340975, 2025).
chronic hepatitis C (3 papers, 2013 to 2017). "In view of the high prevalence of severe vitamin D deficiency in patients with chronic hepatitis C, we therefore sought to investigate the association between genetic variations in CYP2R1, GC, and DHCR7 and HCV-induced HCC." (PMID 23734184, 2013). "Association of SNPs in CYP2R1, GC, and DHCR7 with response to treatment of pegylated interferon-α and ribavirin in patients with chronic hepatitis C." (PMID 23734184, 2013). "Association of SNPs in CYP2R1, GC, and DHCR7 with liver fibrosis progression rate (FPR) in patients with chronic hepatitis C." (PMID 23734184, 2013). "Single functional nucleotide polymorphisms of genes of CYP2R1, GC and CYP27B1 are known to influence the vitamin D serum levels but it is still unknown if they could have a clinical significance in influencing the success of antiviral therapy of chronic hepatitis C." (PMID 24244713, 2013). "Associations between CYP2R1, GC, and DHCR7 genotypes that are determinants of reduced 25-hydroxyvitamin D (25[OH]D3) serum levels and the risk of HCV-related HCC development were investigated for 1279 chronic hepatitis C patients with HCC and 4325 without HCC, respectively." (PMID 23734184, 2013).
colon cancer (3 papers, 2021 to 2025). "Furthermore, the CYP2R1 SNPs rs12785878, rs1790349, and rs12794714 may serve as biomarkers for cancer susceptibility, and the rs12794714‐A allele was linked to a decreased risk of colon cancer." (PMID 38967113, 2024).
gestational diabetes mellitus (3 papers, 2015 to 2025). "Polymorphisms in the CYP2R1 gene have been linked to variations in VD levels and conditions such as spontaneous abortion and gestational diabetes mellitus." (PMID 39585165, 2024). "Dysregulation of vitamin D metabolism—such as downregulation of CYP2R1 and VDR—has been linked to gestational diabetes and preeclampsia and may impair calcium signaling and increase oxidative stress, thereby reducing neonatal bone mineral content." (PMID 40590014, 2025).
hepatocellular carcinoma (3 papers, 2013 to 2026). A malignant tumor that arises from hepatocytes. "Summary of associations between SNPs in CYP2R1, GC, and DHCR7, and HCV-related hepatocellular carcinoma development." (PMID 23734184, 2013).
hypogonadism (3 papers, 2019 to 2025). A disorder characterized by decreased function of the gonads. "Patients with hypogonadism have frequently low levels of 25-hydroxyvitamin D due to impairment of the hydroxylating enzyme CYP2R1 in the testis." (PMID 31015830, 2019). "However, even if the correlation between vitamin D and hypogonadism is not entirely clear, it must be considered that the expression of hydroxylases (CYP2R1 and CYP27B1) and VDR in testis tissue also represents a further indication of the importance of the testicles in the metabolism of vitamin D." (PMID 34067977, 2021).
lung carcinoma (3 papers, 2018 to 2024). "In our study, we found that CYP2R1 rs10741657 was related to the prognosis of lung cancer, and the ‘AA’ genotype was associated with reduced risk of NSCLC death." (PMID 31625015, 2020). "We and others also found that expression of CYP27B1 and CYP2R1 differed by their genotypes in certain SNPs and the expression was associated with lung cancer survival." (PMID 31625015, 2020). "We genotyped 296 SNPs in CYP2R1, CYP27A1, CYP27B1, CYP24A1, and VDR and observed associations between 27 SNPs and lung cancer status after the adjustment for age, gender, and race, all of which had passed the Hardy–Weinberg equilibrium assessment." (PMID 29726119, 2018). "We further genotyped 296 SNPs in the same subjects (N = 761) in CYP2R1, CYP27A1, CYP27B1, CYP24A1, and VDR genes directly involved in vitamin D metabolism, with an objective to elucidate variants that may modulate vitamin D levels, thereby potentially explaining their associations with lung cancer." (PMID 29726119, 2018). "Our meta-analysis revealed the lack of association of CYP2R1 (rs10741657), CYP27B1 (rs3782130), CYP27B1 (rs10877012), CYP24A1 (rs6068816), CYP24A1 (rs4809960), CYP3A5 (rs776746), GC (rs7041), GC (rs4588), and VDR (ApaI: rs7975232) with lung cancer." (PMID 38482381, 2024).
multiple sclerosis (3 papers, 2021 to 2025). A progressive autoimmune disorder affecting the central nervous system resulting in demyelination. "For instance, VitD deficiency has been linked to an increased risk of multiple sclerosis, and genetic polymorphisms in CYP2R1 and CYP27B1 have been associated with multiple sclerosis severity." (PMID 40152347, 2025).
Non-alcoholic Fatty Liver Disease (3 papers, 2021 to 2024). "Additionally, CYP2R1 and DHCR7 are related to vitamin D metabolism, LIPA is associated with non-alcoholic fatty liver disease, and CYP21A1 affects animal development." (PMID 39376613, 2024).
non-small cell lung carcinoma (3 papers, 2018 to 2023). A group of at least three distinct histological types of lung cancer, including non-small cell squamous cell carcinoma, adenocarcinoma, and large cell carcinoma. "Some SNPs on VDR, GC, CYP2R1, CYP24A1, and CYP27B1 were associated with higher risk of non-small cell lung cancer (NSCLC) in Chinese people, and some SNPs on CYP2R1 and CYP27B1 were associated with the rate of FEV1 change over a ten-year period." (PMID 30249031, 2018).
allergic rhinitis (2 papers, 2015 to 2019). Inflammation of the nasal mucous membranes caused by an IgE-mediated response to external allergens. "Based on these previous findings, we hypothesize that VDR and CYP2R1 are candidate genes for susceptibility to allergic rhinitis." (PMID 26177022, 2015).
cholestasis (2 papers, 2021 to 2024). Impairment of the bile flow caused by obstruction within the liver, or outside the liver in the bile duct system. "We investigated the effect of differential expression of CYP2R1 in hepatocytes on the expression of genes related to liver fibrosis in primary hepatic stellate cells (HSCs) of BA and animal models of cholestasis." (PMID 34615940, 2021).
coronary heart disease (2 papers, 2021 to 2025). "Propose: Cytochrome P450 family 2 subfamily R member 1 (CYP2R1) variations can affect the activity of 25-hydroxylase, resulting in the deficiency of 25(OH)D, which leads to an increased incidence and mortality of coronary heart disease (CHD)." (PMID 34262949, 2021).
eczema (2 papers, 2015 to 2017). "Furthermore two CYP2R1 haplotypes increased eczema risk whereas one vitamin D receptor haplotype lowered eczema risk." (PMID 26239464, 2015). "A vitamin D-related SNP on CYP27A1 was also found to be protective against eczema, whereas CYP2R1 and VDR haplotypes appear to alter eczema susceptibility." (PMID 28486474, 2017). "GC rs7041 and CYP2R1 rs7935792 also interacted to modulate total IgE among these Chinese eczema patients." (PMID 26239464, 2015).
hyperglycaemia (2 papers, 2018 to 2022). "The AG + GG genotype (dominant model) of the rs2060793 CYP2R1 polymorphism was associated with hyperglycemia protection (OR = 0.28, 95%CI = 0.08–0.92, p = 0.037)." (PMID 36364874, 2022). "On individually evaluating the MS components, we identified an association between SNP rs10741657 (recessive model) of the CYP2R1 and hyperglycemia." (PMID 36364874, 2022). "On the other hand, SNP rs2060793 (dominant model) of the CYP2R1 was associated with protection from hyperglycemia." (PMID 36364874, 2022). "Our findings have revealed, for the first time, that new variants of the CYP2R1, which have not yet been reported in the literature, are associated with hyperglycemia." (PMID 36364874, 2022).
hyperlipidemia (2 papers, 2022 to 2024). "In conclusion, the rs10741657 G-allele in CYP2R1 was found to be associated with increased levels of HDL-C as well as an elevated risk of hyperlipidemia within the Han Chinese population." (PMID 39560594, 2024). "The G-allele of CYP2R1-rs10741657 was found to be associated with an increased risk of hyperlipidemia and higher levels of HDL-C in controls." (PMID 39560594, 2024). "In our study, we found that the rs10741657 G-allele in CYP2R1 was associated with an increased risk of hyperlipidemia and higher levels of HDL-C in controls." (PMID 39560594, 2024). "The genetic analyses revealed that the G-allele of CYP2R1-rs10741657 was significantly associated with an increased risk of hyperlipidemia in both sepsis (OR = 2.333, 95% CI: 1.227–4.436, P = .010) and polytrauma groups (OR = 4.000, 95% CI: 2.048–7.811, P < .001)." (PMID 39560594, 2024). "As for the specific molecular mechanism research on how hyperlipidemia affects Cyp2r1 expression, it was still lacking." (PMID 35592626, 2022).
liver fibrosis (2 papers, 2013 to 2021). "Therefore, it can be concluded from this study that deficiency of active vitamin D in BA can promote the formation of liver fibrosis, and the main reason for this deficiency is deficiency of CYP2R1, which leads to disorder of vitamin D activation." (PMID 34615940, 2021).
pancreas cancer (2 papers, 2013 to 2015). "For example, pancreas cancer risk was inversely associated with CYP2R1 rs10741657 (AA versus GG, OR = 0.70; 95%CI: 0.51–0.95) and positively with CYP24A1 rs6127119 (TT versus CC." (PMID 23826131, 2013). "Consistent with the findings from the log-additive models, several SNPs in CYP24A1 and CYP2R1 were significantly associated with pancreas cancer risk, including CYP24A1 rs6127119 (TT versus CC." (PMID 23826131, 2013). "Although none of our associations were significant after adjustment for multiple comparisons, minor homozygotes in several SNPs in the CYP2R1 gene, including rs10741657, rs2060793, rs12794714, were associated with a 20–30% change in pancreas cancer risk." (PMID 23826131, 2013). "SNPs in the CYP24A1, CYP2R1, calcium sensing receptor (CASR), vitamin D binding protein (GC), retinoid X receptor-alpha (RXRA) and megalin (LRP2) genes were significantly associated with pancreas cancer risk." (PMID 23826131, 2013).
renal cell carcinoma (2 papers, 2022 to 2023). "However, some studies have shown an association between polymorphisms of CYP2R1 and cancer risk (e.g., breast) or suggested altered gene expression in tumor cells (e.g., renal cell carcinoma)." (PMID 36362448, 2022). "Previous study identified a significant increase in CYP2R1 expression in renal cell carcinoma tissues." (PMID 37644572, 2023).
rheumatoid arthritis (2 papers, 2020 to 2024). A chronic, systemic autoimmune disorder characterized by inflammation in the synovial membranes and articular surfaces. "One study discovered an association between the GG genotype of the CYP2R1 (rs10741657) SNP and decreased calcidiol levels in rheumatoid arthritis patients from Spain." (PMID 38534213, 2024).
Sepsis (2 papers, 2024 to 2025). Sepsis is defined as life-threatening organ dysfunction caused by a dysregulated host response to infection. "The study explored the associations among CYP2R1 polymorphisms, lipid concentrations, and sepsis." (PMID 39560594, 2024). "In conclusion, the G-allele of CYP2R1-rs10741657 could elevate high-density lipoprotein cholesterol levels and protect against sepsis development." (PMID 39560594, 2024). "Therefore, we aim to study the relationship between CYP2R1 gene polymorphisms and lipid profiles in sepsis in order to provide a theoretical basis for its prevention and treatment." (PMID 39560594, 2024). "Therefore, CYP2R1-rs10741657 G-allele might elevate HDL-C levels and protect against sepsis development." (PMID 39560594, 2024).
thyroid cancer (2 papers, 2019 to 2022). "In conclusion, our data suggest that DHCR7 rs12785878 is a novel risk locus for thyroid cancer and that CYP2R1 rs2060793 may confer a protective effect against disease progression." (PMID 31357732, 2019). "CYP2R1 mRNA was detected in both normal thyrocytes and various thyroid cancer subtypes (including anaplastic, papillary, and follicular thyroid cancer)." (PMID 36362448, 2022). "The aim of this study was to determine if the DHCR7 rs12785878, CYP2R1 rs2060793, and CYP24A1 rs6013897 SNPs are also associated with susceptibility to thyroid cancer." (PMID 31357732, 2019).
cardiac arrhythmia (1 paper, 2025). Any disturbances of the normal rhythmic beating of the heart or MYOCARDIAL CONTRACTION. "However, despite these limitations, our results remain robust after Bonferroni correction, confirming associations between CYP2R1 rs10741657 and CYP27B1 rs3782130 with general CVD risk, as well as CYP27B1 rs3782130 and CYP27B1 rs4646536 with cardiac arrhythmias." (PMID 40237935, 2025).
chronic hepatitis B (1 paper, 2017). "Genotype frequencies of DHCR7, CYP27B1, CYP2R1, GC and VDR in HBeAg-positive chronic hepatitis B patients treated with PegIFN for 48 weeks." (PMID 28296915, 2017).
colitis (1 paper, 2018). Inflammation of the colon. "Neither liver CYP2R1 nor kidney CYP27B1 mRNA levels changed significantly with the induction of colitis." (PMID 30065252, 2018).
differentiated thyroid carcinoma (1 paper, 2019). Differentiated thyroid carcinoma (DTC), also known as papillary or follicular thyroid carcinoma, is a slow-growing malignancy usually presenting in adults as an asymptomatic thyroid mass. "Five hundred patients with differentiated thyroid cancer and 500 controls were genotyped for the DHCR7 rs12785878, CYP2R1 rs2060793, and CYP24A1 rs6013897 variants." (PMID 31357732, 2019).
endometriosis (1 paper, 2021). The growth of functional endometrial tissue in anatomic sites outside the uterine body. "Moreover, overexpression of several genes including Cyp2r1, Fabp4, Mrc1, and Rock2 has been shown in the liver and visceral adipose tissue of endometriosis cases." (PMID 34806344, 2021).
gastric cancer (1 paper, 2021). A primary or metastatic malignant neoplasm involving the stomach. "CYP2R1 rs12794714, CYP24A1 rs2762934, rs6068816, and VDR rs11574129 had been reported to be involved in the genetic background of multiple diseases including diabetic ischemic stroke, gastric cancer, and other diseases." (PMID 34925313, 2021).
glaucoma (1 paper, 2024). Increased pressure in the eyeball due to obstruction of the outflow of aqueous humor. "Here, we also used variants in the CYP2R1, CYP27A1 and CYP27B1 genes for evidence of association with glaucoma." (PMID 39202443, 2024).
Hashimoto thyroiditis (1 paper, 2025). An autoimmune disorder caused by the production of autoantibodies against thyroid tissue. "The bar charts revealed mild, group-specific variations, particularly in CYP2R1 and GC polymorphisms within the ASD group and in VDR variants within the Hashimoto’s thyroiditis group." (PMID 41340975, 2025). "However, subtle yet notable differences were observed, particularly in CYP2R1 and GC polymorphisms within the ASD group and in VDR variants within the Hashimoto’s thyroiditis group." (PMID 41340975, 2025).
head and neck cancer (1 paper, 2023). A primary or metastatic malignant neoplasm affecting the head and neck. "Another study examined the influence of genetic sequence variants (GSVs) in the vitamin D3 metabolism pathway, candidate-based GSVs, i.e., VDR, GC, CYP24A1, CYP27A1, CYP27B1, and CYP2R1, on overall survival (OS) and second primary cancer (SPC) in head and neck cancer patients." (PMID 37299554, 2023).
Insulin resistance (1 paper, 2025). Increased resistance towards insulin, that is, diminished effectiveness of insulin in reducing blood glucose levels. "Conversely, CYP2R1, a key microsomal vitamin D hydroxylase, remained unchanged in response to insulin resistance." (PMID 39906623, 2025).
liver dysfunction (1 paper, 2016). "On the contrary, microsomal CYP2R1, the key enzyme for vitamin D synthesis under normal physiological conditions and may be less affected by liver dysfunction, was upregulated." (PMID 27399065, 2016).
metastatic disease (1 paper, 2019). "Our study revealed a decreased frequency of the CYP2R1 rs2060793 (G > A) minor allele in patients with metastatic disease (OR 0.61, 95% CI 0.40–0.93), which suggests a protective effect of this SNP against more advanced disease." (PMID 31357732, 2019).
ovarian carcinoma (1 paper, 2019). A malignant neoplasm originating from the surface ovarian epithelium. "For ovarian cancer dataset, the genes CYP2R1 and HLA-DOB detected by the proposed gsslasso method, were also detected by both lasso and cMCP methods." (PMID 30813883, 2019).
peripheral vascular disease (1 paper, 2025). Any disorder affecting blood flow through the veins or arteries outside of the heart. "For peripheral vascular disease (n = 85 cases), CYP2R1 rs10741657 showed associations across all inheritance models." (PMID 40237935, 2025).
rectal cancer (1 paper, 2019). A primary or metastatic malignant neoplasm that affects the rectum. "In addition to SMAD7 (P = 0.0005) and SMAD3 (P = 0.0003), several other genes or genetic regions (CYP2R1, CHAF1A, CREBBP, IL10, SNPs identified in genome-wide association studies (GWAS) to be associated with IGF levels, IGFBP2/IGFBP5, IGFBP3, and C-MYC region) were associated with rectal cancer." (PMID 31434255, 2019).
sarcopenia (1 paper, 2022). Progressive decline in muscle mass due to aging which results in decreased functional capacity of muscles. "The results of this study demonstrate that GG allelic variations in CYP2R1 (rs10741657), GC (rs2282679) and VDR (rs2228570) genes affect a patient’s vitamin D sufficiency status that may increase the risk of sarcopenia." (PMID 36233147, 2022). "Allelic variations in CYP2R1 (rs10741657), GC (rs2282679), and VDR (rs10741657) affect vitamin D levels and decisively influence the degree of sarcopenia in institutionalized elderly people." (PMID 36233147, 2022). "In this study, we investigated the connection between CYP2R1 (rs10741657), GC (rs2282679) and VDR (rs2228570) on serum 25-OH/D concentrations and the relationship to the degree of sarcopenia in institutionalized elderly people." (PMID 36233147, 2022). "Against this background, we set out to conduct a study on institutionalized elderly, to evaluate the impact and presence of a possible connection between CYP2R1 (rs10741657), GC (rs2282679), and VDR (rs2228570), serum 25-OH/D concentrations and the link with the degree of sarcopenia in older adults." (PMID 36233147, 2022).